THBS1 (thrombospondin 1)
Diseases named in the same sentence as THBS1 in open-access papers (continued):
Sharing a sentence is not in itself a finding about the gene and the disease.
thyroid cancer (9 papers, 2013 to 2025). "On the one hand, Giuseppe and colleagues found a significant reduction in THBS1 expression associated with patients presenting thyroid carcinoma metastasis." (PMID 34268116, 2021). "Camptothecin is a DNA topoisomerase I inhibitor that blocks DNA synthesis and down-regulates THBS1 expression in human thyroid carcinoma FTC-133 cells through the JNK/ATF-2 pathway." (PMID 33746571, 2021).
asthma (8 papers, 2010 to 2024). "The THBS1 gene has been implicated in the response to stress in asthma and in the cellular immunity activity in allergic asthma, corroborating with the high levels in eosinophilic asthma demonstrated in our study." (PMID 38542471, 2024). "To validate the mechanism of THBS1 in vivo, we evaluated OVA + CIH-induced asthma in THBS1-overexpressed mice by injecting adeno-associated viruses (AAV-THBS1)." (PMID 37783703, 2023). "The THBS1 gene has been implicated in the network underlying the pulmonary response to oxidative stress in asthma." (PMID 20513247, 2010). "This suggests that FSIP1 might have an effect on aspirin hypersensitivity in asthma, with relation to the nearby potential gene of THBS1." (PMID 20513247, 2010). "In addition, MMP1 and THBS1 each connect two genes with potential role in severe equine asthma though not yet associated with asthma in humans or mice." (PMID 28886691, 2017). "Our findings confirm that THBS1 participates in CIH-potentiated autophagy by interacting with BECN1 in cellular and murine models of asthma." (PMID 37783703, 2023).
breast tumor (8 papers, 2010 to 2025). "Quiescent tumor-associated endothelium secreted thrombospondin-1 (TSP1) that established a dormant niche to sustain the inactivity of invasive breast tumor cells, a phenotype that was also reported in another study of breast cancer dormancy." (PMID 37887354, 2023). "Thrombospondin-1 (THBS1) is a matricellular ECM protein that can promote breast tumor migration and invasiveness via the activation of diverse signaling pathways including FAK signaling." (PMID 38937754, 2024). "The endothelium has been shown to promote breast tumour cell dormancy via the expression and release of thrombospondin-1 (TSP-1)." (PMID 36701089, 2023). "In ovarian and breast tumor specimens, TGFβI expression was shown to be tightly co-regulated with other genes that induce paclitaxel sensitivity, such as the adhesion glycoprotein, THBS1." (PMID 20576088, 2010). "In the context of tumor evasion, aberrant upstream THBS1 and THBS2 provoke overactivation of MGAT1, leading to enhanced CD73 glycosylation and membrane-bound accumulation, especially in immune-cold breast tumors." (PMID 40229283, 2025).
fibrosis (8 papers, 2013 to 2025). the formation of excess fibrous connective tissue in an organ or tissue in a reparative or reactive process. "Under normal physiological conditions, the liver produces low concentrations of THBS1; however, in pathological conditions, such as alcohol cirrhosis, fibrosis, and nonalcoholic steatohepatitis, the up-regulation of THBS1 was noted." (PMID 40489480, 2025). "This study contributes to the existing literature by identifying THBS1 and the JAK2/STAT3 pathway as promising molecular targets for therapeutic intervention in RILI-associated fibrosis, offering a feasible mechanistic basis for future antifibrotic strategies." (PMID 41394148, 2025). "In the current study, we employed this co-culture system to investigate the therapeutic potential of targeting THBS1 in fibrosis treatment." (PMID 39431015, 2024). "By retracing the interaction between macrophages and HSC, we found that Thbs1 was derived from macrophages in the fibrosis model, and communicated with HSCs by interacting with the aVb3 (Itgb3) and a2Bb3 (Itga2b&Itgb3) complex receptors." (PMID 37724132, 2023). "The top canonical pathways included genes involved in hepatic fibrosis, angiogenesis inhibition by thrombospondin 1 (TSP-1), retinoic acid receptor (RAR) activation, antigen presentation and axonal guidance signaling." (PMID 24344983, 2013).
glaucoma (8 papers, 2016 to 2023). Increased pressure in the eyeball due to obstruction of the outflow of aqueous humor. "For each of the 4 clusters, notable genes associated with glaucoma, neuroinflammation, or reactive astrocytes were: Cluster 1 (Nrf2, Hspb1, S100β), Cluster 2 (Ptgs2, Clcf1), and Cluster 4 (C2, Tlr4, Lcn2, H2-T23, Thbs1, Il6ra)." (PMID 37759301, 2023). "In summary, we have identified THBS1 missense alleles in children severely affected by early-onset glaucoma in 3 unrelated and ethnically diverse families." (PMID 36453543, 2022). "Our results suggest that THBS1 mutations contributed to the development of some cases of early-onset glaucoma, expanding the number of genes responsible for this devastating form of glaucoma." (PMID 36453543, 2022). "Recently a new gene variant of THBS1 was identified in a family with primary open angle glaucoma with elevated intraocular pressure that encodes the known N700S missense mutation." (PMID 35693935, 2022). "In human TM cells, cellular stresses related to glaucoma, including exposure to dexamethasone, can increase THBS1 expression, while Thbs1-null mice have lower IOP and higher aqueous humor outflow compared with WT mice." (PMID 36453543, 2022). "Here, we identified heterozygous thrombospondin 1 (THBS1) missense alleles altering p.Arg1034, a highly evolutionarily conserved amino acid, in 3 unrelated and ethnically diverse families affected by congenital glaucoma, a severe form of glaucoma affecting children." (PMID 36453543, 2022). "Interestingly, we found 8 genes (FN1, THBS1, EPHB2, FGF2, DAB2, CD9, PLAUR and ITGA4) were crucial, suggesting that these genes might function as key factors in the pathogenesis of glaucoma." (PMID 31680442, 2020).
viral infection (8 papers, 2011 to 2025). "Furthermore, previous studies reported that THBS1 was related to apoptosis which was an important immune mechanism used by cells against viral infection." (PMID 31963559, 2020). "To further investigate the impact of THBS1 and ITGAL on WT virus replication, we overexpressed these two genes in Vero E6 cells prior to viral infection and monitored viral replication levels at 12, 24, 48, and 72 hpi." (PMID 40927453, 2025). "The pro-inflammatory monocytes also highly expressed THBS1, PRS20, and IL32 genes, which are involved in viral infection, immune activation, and pro-inflammatory responses." (PMID 36626090, 2023).
cervical cancer (7 papers, 2007 to 2024). A primary or metastatic malignant neoplasm involving the cervix. "First, we searched the underlying targets of circRNA THBS1 in cervical cancer, and the data suggested that circRNA THBS1 sponged to miR-543, suggesting a possible relationship of circRNA THBS1 and miR-543 in cervical cancer." (PMID 37465349, 2023). "RT-qPCR analysis revealed that circRNA THBS1 was upregulated and miR-543 was downregulated in cervical cancer patient tissues, compared to normal paracancer tissues." (PMID 37465349, 2023). "The level of circRNA THBS1 was obviously higher in cervical cancer cell lines than that in Ect1/E6E7 cells." (PMID 37465349, 2023). "The findings indicated that knockdown of circRNA THBS1 inhibited the malignant biological behavior of cervical cancer cells by miR-543/HMGB2 axis." (PMID 37465349, 2023). "Our findings strongly showed that circRNA THBS1 regulates cervical cancer cell proliferation, apoptosis, and EMT via regulating miR-543/HMGB2 axis." (PMID 37465349, 2023). "It is necessary to further study the effect of circRNA THBS1 in cervical cancer cells and analyze the potential molecular regulation mechanism." (PMID 37465349, 2023). "Our data revealed that circRNA THBS1 was significantly upregulated and miR-543 was low expressed in cervical cancer tissues and cell lines." (PMID 37465349, 2023). "Based on these findings, we revealed that circRNA THBS1 negatively regulated miR-543 levels in cervical cancer cells." (PMID 37465349, 2023). "The findings of the current study indicated that circRNA THBS1 was significantly upregulated and miR-543 was low-expressed in cervical cancer tissues and cell lines." (PMID 37465349, 2023). "In conclusion, circRNA THBS1 silencing inhibited the malignant biological behaviors of cervical cancer cells via the regulation of miR-543/HMGB2 axis." (PMID 37465349, 2023). "We also evaluated the levels of circRNA THBS1 and miR-543 in cervical cancer tissues and cervical cancer cell lines, and the data indicated that circRNA THBS1 was significantly upregulated and miR-543 was downregulated in cervical cancer tissues and cervical cancer cell lines." (PMID 37465349, 2023). "Besides, our data revealed that circRNA THBS1-siRNA inhibited the EMT of cervical cancer cells, as confirmed by enhanced E-cadherin expression and suppressed N-cadherin level." (PMID 37465349, 2023). "Nevertheless, little is known about circRNA THBS1’s mechanism in cervical cancer development." (PMID 37465349, 2023). "However, the role and mechanism of circRNA THBS1 in cervical cancer is still unclear." (PMID 37465349, 2023). "Therefore, we hypothesized that circRNA THBS1 may play a role in cervical cancer by regulating the expression of miR-543." (PMID 37465349, 2023). "Thus, we speculated that circRNA THBS1 downregulation or miR-543 upregulation may prevent tumorigenesis in cervical cancer." (PMID 37465349, 2023). "In cervical cancer, IGFBP3 inhibits tumor angiogenesis by intracellular regulation of THBS1 expression." (PMID 35966888, 2022). "circRNA THBS1 silencing inhibited cervical cancer cell proliferation and EMT and induced cell apoptosis via the regulation of miR-543/HMGB2 axis, suggesting its carcinogenic role in cervical cancer." (PMID 37465349, 2023). "However, all these findings were reversed by miR-543 inhibitor, suggesting that silencing of circRNA THBS1 had available proliferation and EMT inhibition, and apoptosis promotion effect in cervical cancer cells." (PMID 37465349, 2023).
endometriosis (7 papers, 2009 to 2025). The growth of functional endometrial tissue in anatomic sites outside the uterine body. "THBS1 may serve as a potential diagnostic biomarker for endometriosis." (PMID 41438033, 2025). "Although recently studies have demonstrated that IL-8 and thrombospondin-1 serum level improve diagnostic reability of ovarian endometriosis we believe that the optimal serum marker should be used to monitoring the response of new antiangiogenic agents used in endometriosis treatment." (PMID 19917115, 2009). "We observed the gene expression levels of THBS1 to be significantly lower in all three disease groups, with the least expression in co-existent adenomyosis–endometriosis cases." (PMID 41272701, 2025). "Overall, our study reveals a significant increase in THBS1 level in ectopic endometrium tissues and validates the potential of THBS1 as a biomarker in endometriosis." (PMID 41438033, 2025). "This approach inevitably introduces selection bias, and we cannot assert that THBS1 is the most critical factor in the pathogenesis of endometriosis." (PMID 41438033, 2025). "Nonetheless, further investigations are warranted to unravel the precise mechanism by which THBS1 contributes to the progression of endometriosis." (PMID 41438033, 2025). "Through lab verification, we revealed the potential role of THBS1 in contributing to the progress of endometriosis." (PMID 41438033, 2025). "Overall, our findings elucidate the role of THBS1 in endometriosis and reveal, both in vivo and in vitro, that THBS1 affects the proliferation, migration, and invasion of cells." (PMID 41438033, 2025). "Elevated TGF-β and THBS1 expression was observed in the ectopic endometrium of patients with endometriosis." (PMID 41438033, 2025). "Although THBS1 has been extensively studied in tumors, research on its role in endometriosis is limited." (PMID 41438033, 2025). "Neoangiogenesis regulators such as Vascular Endothelial Growth Factor A (VEGFA) and Thrombospondin-1 (THBS1) have been involved in the pathology of endometriosis." (PMID 30037059, 2018). "However, SERPINA1 and THBS1 were found to be significantly downregulated in these women relative to endometriosis." (PMID 41272701, 2025). "A deeper exploration of these populations was beyond the scope of this study, but such analyses will be important in future work to clarify the broader cellular context of THBS1 activity and to identify additional pathways that may drive endometriosis." (PMID 41438033, 2025). "Therefore, the objective of this study was to further investigate the significance of THBS1 in the endometriosis using in vitro and in vivo experiments, clinical sample validation, and bioinformatics analysis." (PMID 41438033, 2025). "The aim of our study was to further investigate thrombospondin-1 serum levels in asymptomatic patients and women with pelvic pain to determine whether this antiangiogenic factor can be used as a serum marker of endometriosis activity." (PMID 19917115, 2009). "Further literature review and integration with our previous single-cell transcriptomic analysis revealed that thrombospondin-1 (THBS1) was significantly upregulated in the ectopic endometrium of patients with endometriosis and may have the potential to serve as a biomarker." (PMID 41438033, 2025). "Next, topological analysis using the cytoHubba plugin in Cytoscape identified MMP7, MMP11, SERPINA1, THBS1, and IGFBP5 as candidate hub genes expressed in both adenomyosis and endometriosis." (PMID 41272701, 2025). "Serum thrombospondin-1 concentration did not correlate with the diameter of the endometriomas and the severity of the endometriosis, assessed according to revised AFS scores." (PMID 19917115, 2009). "Recently, Ohata has been demostrated that thrombospondin-1 serum levels were higher in patients with ovarian endometrioma than in patients without endometriosis." (PMID 19917115, 2009).
endometriosis (continued). "Moreover, cyto-hub gene analysis revealed that CSNK2A1, CSNK2A2, TOP1, PRKACA, RBM39 (plasma), ALB, ACTB, GAPDH, FN1, APOA1 (serum), S100-A9, CXCL1, IL1RN, CSTA, S100-A8 (menstrual blood) and THBS1, ALB, CD44, ANXA2, and LUM (urine) were the top 5 proteins expressed in women with endometriosis." (PMID 39061077, 2024).
lymphoma (7 papers, 2013 to 2024). A malignant (clonal) proliferation of B- lymphocytes or T- lymphocytes which involves the lymph nodes, bone marrow and/or extranodal sites. "This cluster is amplified in several types of lymphoma and solid tumours and regulates vascular integrity and angiogenesis, promoting tumour neovascularization in vivo by downregulating antiangiogenic THBS1 (thrombospondin 1)." (PMID 25197665, 2014).
neuroblastoma (7 papers, 2009 to 2022). Neuroblastoma (NB) is the most common solid, extracranial childhood tumor. "Additionally, an initial analysis has also demonstrated the presence of differential profiles of histone modifications at the loci of some differentially methylated genes (i.e., THBS1) in neuroblastomas, highlighting the complexity of epigenetic processes that may be involved in these tumors." (PMID 24212967, 2011).
atrial fibrillation (6 papers, 2021 to 2022). A disorder characterized by an electrocardiographic finding of a supraventricular arrhythmia characterized by the replacement of consistent P waves by rapid oscillations or fibrillatory waves that vary in size, shape and timing and are accompanied by an irregular ventricular response. "In patients with atrial fibrillation, inhibition of miR-4443 can increase the level of THBS1 expression, thereby promoting the invasion of cardiac fibroblast." (PMID 36250718, 2022). "Furthermore, hsa-miR-4443 protected atrial fibrillation (AF) by targeting THBS1, as a biomarker in the development of AF and AF-related complications." (PMID 36212039, 2022). "Most importantly, it has been reported that hsa-miR-4443 is implicated in atrial fibrillation regulation; that is, in atrial fibrillation, hsa-miR-4443 regulates TGF-β1/α-SMA/collagen signaling via targeting THBS1, thereby inhibiting cardiac fibroblast proliferation." (PMID 36204659, 2022). "In the serum of atrial fibrillation (AF) patients, the expression of miR-4443 was significantly reduced, thereby up-regulating the expression level of thrombospondin 1 (THBS1), promoting the proliferation of human cardiac fibroblasts (HCFB), and attenuating cell apoptosis." (PMID 36250718, 2022).
colitis (6 papers, 2017 to 2023). Inflammation of the colon. "The importance of THBS1 in mediating anxiety-associated colitis was confirmed by the reversal effect of recombinant THBS1 on colitis in c-Jun∆AgRP mice." (PMID 36641530, 2023). "Finally, the levels of secreted protein thrombospondin 1 (THBS1) are negatively associated with increased anxiety and colitis, and supplementing recombinant THBS1 rescues colitis susceptibility in c-Jun∆AgRP mice." (PMID 36641530, 2023). "While TGF-β seems to be the key player in both CIA and colitis, its precise mechanism remains to be determined, in particular its association with other factors that bind to several proteins (e.g., the opsonins C1q or Thbs1)." (PMID 36389733, 2022). "Knockout of THBS1 expression in MSCs abolished their therapeutic effects in colitis and the induction of IL-10-producing B cells." (PMID 35371051, 2022). "The gene expression profile revealed that thrombospondin-1 (THBS1) was dramatically upregulated in MSCs after coculture with peritoneal lavage fluid from colitis mice." (PMID 35371051, 2022). "Furthermore, we identified the secreted protein THBS1 function in linking anxiety and colitis and as a biomarker for anxiety-colitis comorbidity." (PMID 36641530, 2023). "The heatmap showed the main genes that were dramatically altered in the extracellular matrix, and we found that THBS1, an adhesive glycoprotein that mediates cell-to-cell and cell-to-matrix interactions, was upregulated in MSCs licensed by peritoneal lavage fluid from colitis mice." (PMID 35371051, 2022). "THBS1-deficient mice exhibited inflammation, with a phenotype similar to that observed in TGFβ-deficient mice, and a more severe course of acute colitis, further supporting the critical role of THBS1 and activating TGF-β in modulating colitis." (PMID 35371051, 2022). "Besides, another THBS1 mimicking peptide, ABT-898, has been shown to alleviate DSS-induced colitis in WT mice." (PMID 36641530, 2023). "Moreover, we reveal the critical role of THBS1, TGF-β, and regulatory B cells in alleviating colitis, providing new insight for the prevention and treatment of IBD." (PMID 35371051, 2022). "Considering that THBS1 could trigger IL-10 production in macrophages, we speculated that THBS1 might participate in MSC-mediated effects on colitis." (PMID 35371051, 2022). "THBS1-KO MSCs and control MSCs were injected intraperitoneally to treat TNBS-induced colitis." (PMID 35371051, 2022). "Here, we found that THBS1 plays an important role in MSC protection against colitis in mice, as the absence of THBS1 in MSCs significantly reversed their immune regulation." (PMID 35371051, 2022). "Mice lacking THBS1 also developed inflammation with a phenotype close to that observed in TGFβ null mice, had more severe course of acute colitis, and displayed colonic inflammation." (PMID 29238343, 2017). "To gain further insights into how anxiety influences colitis, we performed proteomic analysis and serum measurement and found that the levels of secreted protein THBS1 were decreased by CRS in a c-Jun dependent manner, suggesting that it may function as downstream in linking c-Jun regulated colitis." (PMID 36641530, 2023).